WFS1 (wolframin ER transmembrane glycoprotein)
Diseases named in the same sentence as WFS1 in open-access papers (continued):
Sharing a sentence is not in itself a finding about the gene and the disease.
iris coloboma (1 paper, 2020). "This is the first time the association of WFS1 p.C505S with iris coloboma has been demonstrated, although CRYGD p.P24T has been widely reported as being associated with congenital cataract, especially in the Eastern Asian population." (PMID 32148946, 2020). "Meanwhile, we firstly described WFS1 gene mutation associated with congenital iris coloboma and enriched its gene mutation spectrum, which may also provide a new sight for gene therapy for this disease." (PMID 32148946, 2020). "In addition, some research indicated that the mutation of WFS1 may also cause cataract, so we cannot exclude the possibility that the joint action of the CRYGD and WFS1 cause cataract and iris coloboma." (PMID 32148946, 2020). "In conclusion, a novel WFS1 p.C505S mutation and a CRYGD p.P24T mutation were found in a family with cataract and iris coloboma, and they were cosegregated from iris coloboma and cataract, respectively." (PMID 32148946, 2020). "We report a novel mutation, WFS1 p.C505S, and a known mutation, CRYGD p.P24T, that cosegregate with iris coloboma and congenital cataract, respectively, in a Chinese family." (PMID 32148946, 2020). "It was thus confirmed that CRYGD c.70C>A and WFS1 c.1514G>C cosegregate with congenital cataract and iris coloboma, respectively." (PMID 32148946, 2020). "Prior to this study, WFS1 p.C505S had not been reported in association with the iris coloboma phenotype." (PMID 32148946, 2020). "A heterozygous mutation, c.1514G>C (p.C505S) in WFS1, was screened in all iris coloboma patients and was absent in subjects without iris coloboma." (PMID 32148946, 2020). "Bioinformatic analyses and three-dimensional structure prediction proved that the three-dimensional structures of WFS1 c.1514G>C (p.C505S), which had not been reported previously, cosegregated with congenital iris coloboma." (PMID 32148946, 2020). "The results may also be relevant in further studies aiming to investigate the molecular pathogenesis of iris coloboma and congenital cataract.WFS1 c.1514G>C (p.C505S), which had not been reported previously, cosegregated with congenital iris coloboma." (PMID 32148946, 2020).
Low-frequency hearing loss (1 paper, 2023). A type of hearing impairment affecting primarily the low frequencies of sound (125 Hz to 1000 Hz). "In addition, autosomal dominant WFS1 mutations have been implicated in non-syndromic low-frequency hearing loss with childhood onset and without any of the other WS1 manifestations." (PMID 36835101, 2023).
melancholic depression (1 paper, 2015). "Similarities between the behavioral responses of gamma-aminobutyric acid-type A receptor, CB1 receptor, or Wfs1 knockout mice and symptoms of melancholic depression have been reported." (PMID 25638817, 2015).
MODY type 2 (1 paper, 2025). "A heterozygous variant, c.1214A>G (HG38, chr4:6301009A>G, depth of coverage 103×), in exon 8 of the WFS1 gene was identified in a father and his child, both of whom were diagnosed with confirmed MODY type 2." (PMID 39859454, 2025).
mucopolysaccharidosis (1 paper, 2022). A group of autosomal recessive or X-linked inherited lysosomal storage disorders affecting the metabolism of mucopolysaccharides, resulting in the accumulation of mucopolysaccharides in the body. "Genetic testing included CMA, Prader-Willi methylation, mucopolysaccharidosis biochemical testing, and GNAS and WFS1 sequencing." (PMID 35362483, 2022).
muscular dystrophies (1 paper, 2023). "However, the impact of WFS1 mutation on muscular dystrophies remains to be explored." (PMID 37759745, 2023).
Nystagmus (1 paper, 2023). Rhythmic, involuntary oscillations of one or both eyes related to abnormality in fixation, conjugate gaze, or vestibular mechanisms. "PAX6 c.221G>A and WFS1 c.2070_2079del were novel heterozygous mutations that are associated with severe congenital cataract even causing blindness in childhood with nystagmus." (PMID 36843716, 2023).
obstructive sleep apnea (1 paper, 2024). "New research indicates that patients with WFS1 mutations have a higher likelihood of developing both obstructive sleep apnea (OSA) and central sleep apnea (CSA)." (PMID 39595565, 2024).
ovarian dysfunction (1 paper, 2025). The inability of the ovaries to function. "Ultimately, 2 overlapping genes, including WFS1 and DRD5, for the neurodevelopment and 4 ovarian dysfunction-related genes, including WFS1, CC2D2A, PROM1 and QDPR, were identified." (PMID 41185014, 2025). "Through analysis of Genecards and OMIM databases, we identified two neurodevelopmental genes DRD5 and WFS1, and four ovarian dysfunction-related genes WFS1, CC2D2A, PROM1, and QDPR, suggesting their roles in the patient’s manifestations." (PMID 41185014, 2025). "Within the deleted region, four candidate genes (WFS1, CC2D2A, PROM1, and QDPR) warrant detailed discussion regarding their potential roles in ovarian dysfunction." (PMID 41185014, 2025).
Premature ovarian insufficiency (1 paper, 2025). Amenorrhea due to loss of ovarian function before the age of 40. "In addition to its critical role in neurodevelopment, WFS1 is expressed in ovarian granulosa cells, and its mutations are associated with premature ovarian insufficiency (POI) in humans." (PMID 41185014, 2025).
Sensorineural hearing impairment (1 paper, 2021). A type of hearing impairment in one or both ears related to an abnormal functionality of the cochlear nerve. "Thus, our results indicate that rats develop progressive, low-frequency neurosensory hearing loss similarly to WS patients, and also position the Wfs1 KO rat as a genetic animal model for studying progressive sensorineural hearing impairment." (PMID 34831417, 2021).
Sleep apnea (1 paper, 2024). An intermittent cessation of airflow at the mouth and nose during sleep is known as sleep apnea. "WFS1 expression affects not only circadian rhythms but also plays a significant role in the development of sleep apnea." (PMID 39595565, 2024). "It has been hypothesized that WFS1’s role in sleep apnea extends beyond mere respiratory control." (PMID 39595565, 2024).
sleep disorder (1 paper, 2024). A change from the patient's baseline sleeping pattern, in the hours slept and/or an alteration/dysfunction in the stages of sleep. "Research has shown that heterozygous subjects with WFS1 mutations have a 26-fold increased risk of hospitalization for psychiatric disorders, many of which are linked to sleep disturbances." (PMID 39595565, 2024). "Due to its involvement in the pathological mechanisms of AD and sleep disorders, WFS1 is regarded as a potential early diagnostic marker for these diseases." (PMID 39595565, 2024). "When WFS1 mutations disrupt this axis, the resulting dysregulation exacerbates both sleep disorders and stress responses." (PMID 39595565, 2024). "Sleep disorders caused by mutations in the WFS1 gene are often associated with psychiatric conditions, such as anxiety, depression, bipolar disorder, and suicidal tendencies." (PMID 39595565, 2024). "This calcium imbalance is one of the main causes of sleep disorders observed in people with mutations in the WFS1 gene." (PMID 39595565, 2024). "Alterations in WFS1 expression are linked to changes in neuronal excitability and neurotransmitter release, which may contribute to the onset or exacerbation of sleep disorders." (PMID 39595565, 2024). "Some studies have suggested a surprising link between alterations in WFS1 expression and the development of AD, as well as various sleep disorders." (PMID 39595565, 2024). "This manuscript aims to explore the current knowledge of WFS1’s involvement in AD and sleep disorders, focusing on its potential as a biomarker and therapeutic target." (PMID 39595565, 2024).
psychiatric disorder (18 papers, 2008 to 2024). A disorder characterized by behavioral and/or psychological abnormalities, often accompanied by physical symptoms. "It is critical to understand wolframin’s role in sleep regulation since heterozygous WFS1 mutations affect around 1% of the population and have a significant potential influence on psychiatric disorders." (PMID 39202345, 2024). "WFS1 heterozygosity has also been associated with metabolic diseases, psychiatric disorders, and even suicidal ideation." (PMID 39202345, 2024). "WS1 patients also experience sleep abnormalities, therefore here we investigate the role of WFS1 in sleep regulation in hope that this will help us better understand the sleep disruptions associated with psychiatric disorders." (PMID 37399203, 2023). "In this study, we applied a multi-dimensional strategy of combining 3D cerebral organoids and 2D neural differentiation derived from hESCs to illuminate the role of the causative gene WFS1 in psychiatric disorders underlying WS." (PMID 36750736, 2023). "WFS1 heterozygosity is a well-established genetic risk factor for the metabolic disorders, psychiatric disorders, and even suicide." (PMID 37759745, 2023). "WFS1 deficiency in neurons autonomously delays neuronal differentiation with altered expressions of genes associated with psychiatric disorders, and impairs neurite outgrowth and synapse formation with elevated cytosolic calcium." (PMID 36750736, 2023). "The most described findings with the heterozygosity of the WFS1 gene are related to the hearing loss and psychiatric diseases." (PMID 37759745, 2023). "Considering the significant divergences in structure, cell types and cognitive capacity between brains of human and experimental animals, lack of proper human disease models limits understanding how WFS1 deficiency contributes to psychiatric disorders in WS." (PMID 36750736, 2023). "In this report, we examined the relationship between reported pathogenic mutations in WFS1 and psychiatric disorders." (PMID 34746052, 2021). "Mutations in the WFS1 gene have been associated with cognitive abnormalities, in particular psychiatric disorders." (PMID 34746052, 2021). "Approximately 1% of the general population are heterozygous carriers of WFS1 gene mutation and it has been found that these carriers have increased risk for developing a psychiatric disease." (PMID 26379490, 2015). "Heterozygous missense mutations in WFS1 have been linked to autosomal dominant low frequency neurosensory hearing impairment and psychiatric disorders." (PMID 25255707, 2014). "The Wolfram syndrome gene (WFS1), previously associated with psychiatric disorders and suicide, was also down-regulated among the suicide victims in the NACC." (PMID 22558144, 2012). "The cause of these psychiatric disorders is still unknown, as it is unclear if these symptoms arise only from stress related to a chronic disease, genetic changes in the WFS1 gene, or a combination of both causes." (PMID 39202345, 2024). "Furthermore, heterozygous carriers of WFS1 mutations exhibit a higher prevalence of psychiatric disorders compared to the general population." (PMID 39595565, 2024). "Moreover, the expression of WFS1 in brain regions associated with emotional regulation, such as the amygdala and hippocampus, suggests a potential link to psychiatric disorders." (PMID 39202345, 2024). "We found that WFS1-deficient cerebral organoids not only phenocopied progressive neuronal loss in WS patients, but also showed impaired synapse formation which underlies common psychiatric disorders, providing a defective structural basis for WS." (PMID 36750736, 2023). "Thus, our study provides mechanistic insights into psychiatric disorders of WS, and highlights the pathogenic role of WFS1-deficient astrocytes and proposes a potential therapeutic approach with Riluzole." (PMID 36750736, 2023).
psychiatric disorder (continued). "However, the mechanisms of how WFS1 deficiency impacts synapse formation underlying psychiatric disorders in WS remain elusive." (PMID 36750736, 2023). "Interestingly, loss of WFS1 activity is also associated with increased risk of psychiatric disorders, as well as juvenile-onset diabetes, progressive neurologic degeneration, and endocrine dysfunction." (PMID 31010095, 2019). "Because WFS1 is highly expressed in the limbic system, which includes the amygdala, the hippocampal region, the olfactory tubercles, and the top layer of the piriform allocortex, it has been proposed that alterations in these brain regions cause psychiatric disorders in WS1 patients." (PMID 39202345, 2024). "Our discovery that WFS1 deficiency-elicited perturbations in Ca2+ homeostasis leads to disturbed mitochondrial dynamics and impaired neuronal development may help us to understand the pathophysiology of some psychiatric disorders." (PMID 27434582, 2016). "To date, specific WFS1 mutations have not been definitively linked to psychiatric disorders in WS1 patients." (PMID 39202345, 2024). "Recent studies have suggested that WFS1 may be a promising target for psychiatric disease research because of the high prevalence of psychiatric disorders among WS1 patients and their families." (PMID 39202345, 2024). "Heterozygous mutations in WFS1 increase the risk of psychiatric disorders without causing WS, although this view has been challenged." (PMID 26379490, 2015). "This could account for an increased risk of mental disorders not just in WS1 patients but also in a subset of heterozygotes with WFS1 mutations." (PMID 39202345, 2024). "Furthermore, since alterations in the gene WFS1 take place in different neurologic and psychiatric disorders, our work may also have broad implications for understanding the role of mitochondrial dynamics in neuropsychiatric diseases." (PMID 27434582, 2016). "The WFS1 gene, originally identified for its involvement in WS1, has since been widely recognized for its broader role in a range of neurological and psychiatric diseases." (PMID 39595565, 2024). "Numerous studies have shown the key role that the WFS1 gene plays in both WS1 and certain neurodegenerative and psychiatric disorders, particularly AD." (PMID 39595565, 2024).
neurodegenerative disease (14 papers, 2010 to 2024). A disorder of the central nervous system characterized by gradual and progressive loss of neural tissue and neurologic function. "Disruptions in these processes caused by WFS1 mutations might lead to increased neuronal degeneration or dysfunction in these sensitive areas, contributing to the progression of neurodegenerative diseases." (PMID 39595565, 2024). "Therefore, elucidating the mechanisms underlying the effects of WFS1 mutations will advance our understanding of neurological and neurodegenerative diseases and lead to the development of therapeutic strategies to halt the progression of WFS1-related disorders." (PMID 29357349, 2018). "WFS1 is a negative regulator of ER stress, a key event involved in the onset of neurodegenerative diseases, by preventing ATF6 activation thereby blocking the expression of proteins (CHOP, ATF4, BIP, and sXBP1) that promote cellular apoptosis." (PMID 36890518, 2023). "The dysfunction of WFS1 is linked to conditions such as WS1 and neurodegenerative diseases." (PMID 39595565, 2024). "WS1, specifically, is characterized by a distinctive WFS1 mutation, leading to early and chronic ER stress, which is not a universal feature in all degenerative diseases." (PMID 39595565, 2024). "Collectively, our findings suggest that by enhancing WFS1 protein expression, THC may protect neurons against ER stress and mitochondrial damage in not only HIV infection but also other inflammation-associated neurodegenerative diseases." (PMID 36890518, 2023). "Additionally, WFS1 plays an essential role in sleep regulation by influencing neuronal excitability and neurotransmitter release, which may explain the sleep disturbances frequently observed in neurodegenerative diseases." (PMID 39595565, 2024). "In fact, both WFS1 and WFS2 (namely, the gene responsible for WS2, the rarer form of WS) seem to be directly and/or indirectly involved in the pathogenesis of several neurodegenerative diseases." (PMID 33693650, 2021).
genetic disorder (10 papers, 2014 to 2025). "Although known as a genetic disease in which endoplasmic dysfunction is considered to be the main cause of beta cell death, it has been reported that mutations in the WFS1 gene that are specific to this disease have been associated with increased systemic inflammation." (PMID 38742118, 2024).
cancer (6 papers, 2017 to 2025). A tumor composed of atypical neoplastic, often pleomorphic cells that invade other tissues. "The five EMRGs in our model—LOXL2, RUNX2, NCKAP1L, WFS1, and SPTBN1—have been implicated in diverse cancer-related processes." (PMID 41164190, 2025). "The PPI network and hub genes analysis indicated that the knockdown of WFS1 had significant influence on carcinogenesis and development of cancer, calcium regulation, signal transduction, dephosphorylation." (PMID 36564540, 2022). "The identification of RPS6KA1 and WFS1 is interesting as previous studies have reported their role in the promotion of tumour progression and metastasis in various cancers." (PMID 32899298, 2020). "In the second dataset all the CGC genes (5/507) were classified as oncogenes by OncoScore and 4 (4/302) out of 5 nCan genes (ALMS1, DCAF17, GPD1L and WFS1) were classified as ‘non-cancer’ at the final time point, as expected." (PMID 28387367, 2017). "Notably, WFS1 exhibited substantial differential expression between the EC group and the control group, characterized by low WFS1 expression in cancer tissues." (PMID 39478865, 2024). "RPS6KA1, WFS1, ANAPC4 and TUBB4A have not been investigated in EC prior to this, and further studies are indicated to elucidate how these genes may affect survival in cancer in general, as well as their role in EC." (PMID 32899298, 2020).